SPRY1 (sprouty RTK signaling antagonist 1)
Description:
Inhibits fibroblast growth factor (FGF)-induced retinal lens fiber differentiation, probably by inhibiting FGF-mediated phosphorylation of ERK1/2 (By similarity). Inhibits TGFB-induced epithelial-to-mesenchymal transition in lens epithelial cells (By similarity).
Synonyms: hSPRY1
Tractability: Antibody: its Gene Ontology location is reachable by antibodies, with high confidence; UniProt places it where antibodies can reach, with medium confidence. PROTAC: ubiquitination databases record sites on it.
Gene: Protein-coding gene on chromosome 4 (123,396,754 to 123,403,760, forward strand). Ensembl gene ENSG00000164056.
Subcellular location: Cytoplasm; Membrane
Subcellular location (Human Protein Atlas): Cytosol; Golgi apparatus; Nucleoplasm
Pathways (Reactome):
Signal Transduction: EGFR downregulation
Gene Ontology:
Molecular function: protein binding; protein kinase inhibitor activity
Biological process: negative regulation of fibroblast growth factor receptor signaling pathway; epithelial to mesenchymal transition involved in cardiac fibroblast development; negative regulation of epidermal growth factor receptor signaling pathway; negative regulation of epithelial to mesenchymal transition; negative regulation of ERK1 and ERK2 cascade; negative regulation of lens fiber cell differentiation; negative regulation of Ras protein signal transduction; negative regulation of transforming growth factor beta receptor signaling pathway; endothelial tube formation; positive regulation of vascular permeability; regulation of signal transduction
Cellular component: cytosol; plasma membrane; cytoplasm; membrane
Genetic constraint (gnomAD): Loss-of-function variants: 20 observed, 23.75 expected, observed/expected ratio (o/e) 0.84, 90% interval 0.59 to 1.22. The upper end of that interval is the gene's LOEUF score, 1.22, which puts it in group 5 of 6, group 1 being the genes least tolerant of losing a copy. Missense variants: 446 observed, 410.15 expected, observed/expected ratio (o/e) 1.09, 90% interval 1 to 1.18. Synonymous variants: 155 observed, 152.05 expected, observed/expected ratio (o/e) 1.02, 90% interval 0.89 to 1.16.
Homologues: Orthologues: chimpanzee SPRY1 (99% identical), macaque SPRY1 (99% identical), pig SPRY1 (97% identical), guinea pig SPRY1 (96% identical), rabbit SPRY1 (96% identical), mouse Spry1 (83% identical), rat Spry1 (83% identical), tropical clawed frog spry1 (77% identical), zebrafish spry1 (55% identical), Drosophila melanogaster sty (31% identical). Paralogues in human: SPRY2 (51% identical), SPRY4 (42% identical), SPRY3 (37% identical).
Diseases named in the same sentence as SPRY1 in open-access papers:
SPRY1 is named in the same sentence as 94 diseases in open-access papers, as found by Europe PMC text mining. Sharing a sentence is not in itself a finding about the gene and the disease. The quoted sentences say what the papers report.
breast carcinoma (17 papers, 2010 to 2025). "Expression of SPRY1 is associated with decreased growth and invasiveness of prostate and breast cancer." (PMID 40867253, 2025). "SPRY1 was reported to be associated with many kinds of tumors, such as breast cancer, colorectal cancer, and human epithelial ovarian cancer (Masoumi‐Moghaddam, Amini, Wei, Robertson, & Morris, 2015)." (PMID 31701684, 2020). "It has been suggested that increased SPRY1 expression leads to inhibition of tumor growth in human breast cancer cells." (PMID 31357584, 2019). "Sprouty (Spry) family genes Spry1, Spry2 and Spry4 are differentially expressed in breast cancer, but Spry3 is rarely expressed." (PMID 31671542, 2019). "To understand Spry1 regulation of signaling events controlling breast cancer phenotype, we used lentiviral delivery of human Spry1 shRNAs to suppress Spry1 expression in MDA-MB-231, an established TNBC cell line." (PMID 26976794, 2016). "The only published report of expression of Sprouty in breast cancer showed decreased expression at transcript level of Spry1 and Spry2 in 78% and 96% respectively of a small panel of breast cancers (n = 50)." (PMID 21909357, 2011). "Sprouty family genes were differentially expressed across the five intrinsic breast cancer subtypes, with high expression of Spry 1 and Spry2 in normal-like cancers and higher expression of Spry4 in basal-like and normal-like cancers." (PMID 21909357, 2011). "SPRY1, part of the mammalian sprouty gene family consisting of four members (SPRY1-4), has tumor suppressive activity and is downregulated in certain tumors such as prostate and breast cancer 25,26." (PMID 32754285, 2020). "For instance, knockdown or overexpression of key miR‐21 target genes—such as SPRY1—in breast cancer cell lines or patient‐derived organoids could help confirm their functional roles in tumor progression and clarify the mechanistic impact of miR‐21 in breast cancer." (PMID 40567015, 2025). "Some studies showed that in a mouse breast cancer model, transforming growth factor beta (TGF-β)-induced EMT was promoted by U2AF65 (an RBP) through Spry1 splicing." (PMID 32670859, 2020). "Collectively, these data strongly suggest that SOX7 activates SPRY1 and SLIT2, but inhibits MTHFD2 and TRIB3 in breast cancer." (PMID 29757932, 2018). "The dysregulated SOS1 and SPRY1 induced by BRCA1 knockdown might therefore inactivate the Ras/MAPK pathway, which has an important role in breast cancer." (PMID 26039571, 2015). "Our lab has already reported that Spry1 is a partner protein of the urokinase-type plasminogen activator receptor (uPAR) which is able to inhibit uPAR-stimulated migration and invasion in the Saos-2 osteosarcoma, MDA-MB-231 breast cancer and HCT116 colorectal cancer cell lines." (PMID 24932220, 2014). "For instance, in prostate and breast cancers SPRY1 and SPRY2 levels are inhibited, whereas in hepatocellular carcinoma only SPRY2 but not SPRY1 expression is decreased." (PMID 26392417, 2015).
triple-negative breast carcinoma (9 papers, 2016 to 2023). An invasive breast carcinoma which is negative for expression of estrogen receptor (ER), progesterone receptor (PR), and human epidermal growth factor receptor 2 (HER2). "Loss of SPRY1 reduces the growth of cutaneous melanoma and suppression of SPRY1 inhibits triple-negative breast cancer malignancy." (PMID 37507768, 2023). "It was reported that knockdown of SPRY1 can reduce the risk of distant metastasis from triple negative breast cancer via inhibiting EGF/EGFR mediated pathways." (PMID 36035369, 2022). "SPRY1, on the other hand, has been associated with increased malignancy in triple-negative breast cancer and has been shown to be downregulated in epithelial ovarian cancer." (PMID 33187334, 2020). "In contrast, a recent study reported that loss of SPRY1 improved the response to targeted therapy in melanoma and suppression of SPRY1 inhibited triple-negative breast cancer malignancy via enhancing the estrogen growth factor and its receptor (EGF/EGFR) mediated mesenchymal phenotype." (PMID 34830836, 2021). "On the other hand, SPRY1 represents an oncogene in triple negative breast cancer cell lines, and was also reported to be overexpressed in hepatocellular carcinoma." (PMID 31357584, 2019). "Additionally, SPRY1 was reported to play a selective role in a subset of triple-negative breast cancers to promote the malignant phenotype by enhancing the EGF-mediated mesenchymal phenotype." (PMID 32634115, 2020).
glioma (8 papers, 2019 to 2025). A benign or malignant brain and spinal cord tumor that arises from glial cells (astrocytes, oligodendrocytes, ependymal cells). "The data in this review demonstrate that SPRY1 is an oncogene in GB because high SPRY1 levels are associated with reduced survival of GB and adult glioma patients." (PMID 41516252, 2025). "Downregulation of SPRY1 reduces the stemness and the self-renewal ability of glioma stem cells, which is important because self-renewal of glioma stem cells is associated with tumor recurrence and therapeutic resistance." (PMID 41516252, 2025). "Recent studies demonstrated that knockdown of SPRY2 enhances CD44 in cancer-associated fibroblasts, whereas knockdown of SPRY1 reduces stemness of patient-derived glioma stem cell spheres." (PMID 39682716, 2024). "In GB tissue, SPRY1 mRNA and protein are significantly upregulated compared to normal brain tissue or lower-grade gliomas, and high SPRY1 levels are related to reduced overall survival of GB patients using the REMBRANDT datasets." (PMID 41516252, 2025). "Bioinformatics results showed that high SPRY1 expression correlates with poor overall survival in glioma patients." (PMID 35910677, 2022). "SPRY1 expression was inhibited in glioma stem cells using small interference RNA (siRNAs) to examine its role in cell proliferation and tumorsphere formation." (PMID 35910677, 2022). "Expression of SPRY1 gene, another potential glioma biomarker that showed comparable characteristics to FREM2 in the previous study, was also associated with survival and showed a similar pattern to FREM2 expression." (PMID 34439271, 2021). "We discovered higher FREM2 and SPRY1 gene expression levels in glioblastomas compared to lower grade gliomas and reference samples." (PMID 31357584, 2019). "We validated the FREM2 and SPRY1 genes and their proteins in glioma tissue samples from different grades with respect to different human cancers and reference samples." (PMID 31357584, 2019). "To further delineate the effects of SPRY1-4 in the tumorigenesis of the nervous system, we analyzed the association of SPRY1-4 with the overall and event/progression-free survival of patients with pediatric and adult glioma, GB, and NB using public datasets." (PMID 41516252, 2025). "Interestingly, SPRY1 mRNA expression was correlated with glioma grades, and higher levels of SPRY1 patients showed a shorter survival rate than those with lower levels of SPRY1 (p. value <.0001)." (PMID 35910677, 2022). "miRNA-21 promotes proliferation of human glioma cells through the PI3K/AKT/SPRY1 pathway." (PMID 33718161, 2021). "Finally, we performed in-silico analysis using TCGA database, which indicated increased FREM2 and SPRY1 gene expression in glioblastomas compared to lower grade gliomas and reference samples." (PMID 31357584, 2019). "Furthermore, the expression of SPRY1 is higher in glioma stem cells than in GB cells." (PMID 41516252, 2025). "We demonstrated that SPRY1 is highly expressed in glioma stem cells than in NHA, glioma cells, and differentiated glioma stem cells." (PMID 35910677, 2022). "Surprisingly, SPRY1 mRNA expression is highly upregulated in GSCs (GSC11, 20, 23, and 267) than in other glioma cells (A172, A1207, LN229, and U87MG) and normal astrocytes, NHA." (PMID 35910677, 2022). "The mRNA expression levels of SPRY1 were confirmed using quantitative reverse transcription PCR (RT-qPCR) in normal human astrocytes (NHA), glioma cells, and glioma stem cells." (PMID 35910677, 2022). "We also found a correlation between the SPRY1 gene expression levels and patients with IDH-WT gliomas that were treated with temozolomide." (PMID 31357584, 2019). "Here, we found that SPRY1 is highly expressed in glioma stem cells, compared to glioma cell lines and non-tumor cells." (PMID 35910677, 2022).
glioma (continued). "Using qPCR, we examined the patterns of the gene expression levels of FREM2 and SPRY1 in glioma tissue samples of different WHO grades, as well as in nonmalignant brain tissue samples." (PMID 31357584, 2019). "At the transcriptomic level, both FREM2 and SPRY1 show increased expression in tissue samples of different glioma grades compared to nonmalignant brain tissue." (PMID 31357584, 2019). "Interestingly, SPRY1 knockdown using siRNA in human GSCs decreases cell growth as well as a sphere-forming ability by repressing CD15 and CD133 expression, which have been used as markers for defining glioma stem cells." (PMID 35910677, 2022). "To evaluate potential use of our previous findings for clinical purposes, we performed a pilot study where we examined the expression of FREM2 and SPRY1 at the proteomic and transcriptomic levels in different grades of gliomas and nonmalignant brain-tissue samples." (PMID 31357584, 2019). "In all cases (glioblastoma IDH-WT, low grade glioma IDH-WT and mutant), SPRY1 expression did not significantly impact upon patient overall survival." (PMID 31357584, 2019).
prostate carcinoma (8 papers, 2007 to 2016). A carcinoma that arises from epithelial cells of the prostate gland. "Surprisingly, we have demonstrated that single germline deletions of either Spry1 or Spry2 result in the development of prostatic intraepithelial neoplasias, the generally accepted precursor of prostate cancer." (PMID 26075267, 2015). "Four candidates (Decorin, SPARC, Spry-1, Tsukushi) were immunolocalised in human foetal prostate (weeks 14, 16, 19) and expression of Decorin was evaluated on a human prostate cancer tissue microarray." (PMID 22880013, 2012). "Using tissue microarrays containing pairs of samples from tumors and normal peripheral tissue, Spry1 was shown to be decreased in 39% of prostate cancer compared with matched normal prostate tissue." (PMID 19662191, 2007). "However, the decreased Spry1 expression in prostate cancer mainly attributes to other mechanisms of gene inactivation such as alterations in transcriptional factors and microRNA mediated post-transcriptional gene silencing." (PMID 26976794, 2016). "In support of a role for Sprouty as a tumour suppressor, proliferation of prostate cancer cell lines (LNCaP and PC3) is suppressed by SPRY1 overexpression." (PMID 26075267, 2015). "However, a considerable fraction of the tumors exhibited a higher expression of Spry1 to the corresponding peripheral tissue indicating that, although decreased Spry1 expression is seen in a substantial fraction of prostate cancers, loss of Spry1 expression is not required in all prostate cancers." (PMID 19662191, 2007). "There are limited reports of SPRY1 and SPRY2 suppression in clinical samples of prostate cancer." (PMID 26075267, 2015). "Of note is our finding that SPRY1 expression does not appear to be significantly reduced in prostate carcinomas." (PMID 26075267, 2015).
melanoma (7 papers, 2012 to 2022). A malignant, usually aggressive tumor composed of atypical, neoplastic melanocytes. "To further validate the inverse correlation between MT1-MMP and SPRY proteins and to determine whether they are expressed in melanoma, we measured the expression levels of SPRY1, SPRY2 and SPRY4 in thirteen metastatic melanoma tumor samples." (PMID 26392417, 2015). "SPRY1 and 2 were also identified as possible MT1-MMP targets, however, neither SPRY1 nor 2 showed any significant correlation with melanoma progression and importantly, did not correlate with MT1-MMP expression in either melanoma cell lines or tumor samples." (PMID 26392417, 2015).
pulmonary fibrosis (6 papers, 2017 to 2024). Chronic progressive interstitial lung disorder characterized by the replacement of the lung tissue by connective tissue, leading to progressive dyspnea, respiratory failure, or right heart failure. "Previous studies have revealed that miR‐21 impacts liver and lung fibrosis progression by activating the SPRY1/ERK/NF‐kB signalling pathway." (PMID 34164910, 2021). "Recently, Ning et al7 and Sun et al8 reported that miR‐21 mediates angiotensin II–induced liver and pulmonary fibrosis via the ERK/NF‐κB pathway by directly targeting SPRY1." (PMID 34164910, 2021). "In conclusion, our study has demonstrated that AngII induction of mir-21 is a crucial factor that mediates pulmonary fibrosis by activating the NLRP3 inflammasome/IL-1β secretion axis via the Spry1/ERK/NF-κB pathway." (PMID 29084974, 2017). "Moreover, protein levels of ERK/NF-κB/NLRP3 and collagen were increased, but the protein level of Spry1 was decreased in BLM-induced pulmonary fibrosis." (PMID 29084974, 2017). "MiR-21 could control pathways such as the TGF-β1 signaling pathway by targeting SMAD7 and SPRY1 or by inhibiting PTEN, which is a known negative regulator of lung fibrosis." (PMID 30658565, 2019). "However, it has not been determined whether mir-21 mediates pulmonary fibrosis via the ERK signaling pathway by targeting Spry1." (PMID 29084974, 2017).
rhabdomyosarcoma (6 papers, 2014 to 2025). A rare aggressive malignant mesenchymal neoplasm arising from skeletal muscle. "Thus, they argued that Spry1 functions as an agonist of ERK signaling in rhabdomyosarcoma with RAS mutation." (PMID 24744103, 2014). "Despite being tumor suppressors in many types of cancer, SPRY1 is an oncogene in rhabdomyosarcoma, SPRY2 in colorectal cancer, and SPRY4 in gastric cancer." (PMID 41516252, 2025). "Accordingly, the tumor-promoting activities of Spry1 in rhabdomyosarcoma were also attributed to its positive regulatory functions within this pathway." (PMID 34769378, 2021). "Spry1 promotes the tumorigenic capacities of rhabdomyosarcoma, while this member of the Spry protein family exerts tumor-suppressive roles in cancers of the prostate and thyroid." (PMID 34769378, 2021). "In case of Spry1, an oncogenic function of the protein was demonstrated in the embryonal subtype of rhabdomyosarcoma." (PMID 31374860, 2019). "In other types of tumors, members of the Spry protein family fulfill a tumor-promoting task as it was demonstrated for Spry2 in colon carcinoma and for Spry1 in rhabdomyosarcoma." (PMID 31374860, 2019). "Silencing of SPRY1 has been found to trigger complete regression of RAS mutant cells in the human childhood rhabdomyosarcoma (RMS)." (PMID 28415695, 2017).